RN7SL310P (RNA, 7SL, cytoplasmic 310, pseudogene)
Gene: Miscellaneous RNA gene on chromosome 18 (50,206,998 to 50,207,278, reverse strand). Ensembl gene ENSG00000240663.
Homologues: Orthologues: chimpanzee Metazoa_SRP (99% identical), macaque Metazoa_SRP (95% identical). Paralogues in human: RN7SL3 (83% identical), RN7SL1 (83% identical), RN7SL2 (81% identical), RN7SL357P (80% identical), RN7SL278P (79% identical), RN7SL498P (79% identical), RN7SL566P (79% identical), RN7SL743P (79% identical), RN7SL220P (79% identical), RN7SL290P (79% identical), RN7SL650P (79% identical), RN7SL411P (78% identical), and 705 more.